ADGRE2 (adhesion G protein-coupled receptor E2)
Description:
Cell surface receptor that binds to the chondroitin sulfate moiety of glycosaminoglycan chains and promotes cell attachment. Promotes granulocyte chemotaxis, degranulation and adhesion. In macrophages, promotes the release of inflammatory cytokines, including IL8 and TNF. Probably signals through G proteins. Is a regulator of mast cell degranulation.
Synonyms: CD312; EMR2; CD97; VBU
Tractability: Antibody: UniProt places it where antibodies can reach, with high confidence; its Gene Ontology location is reachable by antibodies, with high confidence; UniProt predicts a signal peptide or a membrane-spanning region. PROTAC: ubiquitination databases record sites on it.
Gene: Protein-coding gene on chromosome 19 (14,732,392 to 14,778,560, reverse strand). Ensembl gene ENSG00000127507.
Subcellular location: Cell membrane; Cell projection, ruffle membrane
Subcellular location (Human Protein Atlas): Vesicles; Cytosol
Pathways (Reactome):
Signal Transduction: Class B/2 (Secretin family receptors)
Gene Ontology:
Molecular function: chondroitin sulfate binding; protein binding; G protein-coupled receptor activity; calcium ion binding; transmembrane signaling receptor activity
Biological process: cell adhesion; cell migration; granulocyte chemotaxis; regulation of mast cell degranulation; G protein-coupled receptor signaling pathway; cell surface receptor signaling pathway; immune system process
Cellular component: leading edge membrane; plasma membrane; membrane; ruffle membrane
Genetic constraint (gnomAD): Loss-of-function variants: 79 observed, 92.71 expected, observed/expected ratio (o/e) 0.85, 90% interval 0.71 to 1.03. The upper end of that interval is the gene's LOEUF score, 1.03, which puts it in group 4 of 6, group 1 being the genes least tolerant of losing a copy. Missense variants: 774 observed, 976.9 expected, observed/expected ratio (o/e) 0.79, 90% interval 0.75 to 0.84. Synonymous variants: 341 observed, 392.74 expected, observed/expected ratio (o/e) 0.87, 90% interval 0.79 to 0.95.
Homologues: Orthologues: chimpanzee ADGRE2 (95% identical), macaque ADGRE2 (89% identical), rabbit ADGRE2 (61% identical). Paralogues in human: ADGRE5 (59% identical), ADGRE3 (43% identical), ADGRE1 (33% identical), ADGRL3 (27% identical), ADGRL1 (26% identical), ADGRL2 (26% identical), ADGRL4 (23% identical), ADGRD1 (21% identical), ADGRG4 (20% identical), ADGRB1 (20% identical), ADGRB2 (20% identical), ADGRG2 (20% identical), and 30 more.
Diseases named in the same sentence as ADGRE2 in open-access papers:
ADGRE2 is named in the same sentence as 42 diseases in open-access papers, as found by Europe PMC text mining. Sharing a sentence is not in itself a finding about the gene and the disease. The quoted sentences say what the papers report.
urticaria (8 papers, 2017 to 2025). A vascular reaction of the skin characterized by erythema and wheal formation due to localized increase of vascular permeability. "EMR2 represents a protein involved in hereditary severe vibratory urticaria, caused by a germline missense mutation in ADGRE2 (p.C492Y)." (PMID 33671092, 2021). "EMR2/ADGRE2 is a human myeloid-restricted adhesion G protein-coupled receptor critically implicated in vibratory urticaria, a rare type of allergy caused by vibration-induced mast cell activation." (PMID 28421075, 2017). "Interestingly, the ADGRE2 C492Y mutation is linked to autosomal dominant vibratory urticaria and HαT." (PMID 39940696, 2025). "The identification of EMR2/ADGRE2 as the vibratory urticaria-inducing molecule attests to the functional importance of this myeloid-restricted aGPCR." (PMID 28421075, 2017).
acute myeloid leukemia (3 papers, 2024 to 2025). Acute myeloid leukemia (AML) is a group of neoplasms arising from precursor cells committed to the myeloid cell-line differentiation. "In acute myeloid leukemia (AML), the expression of the ADGRE2 antigen and CLEC12A antigen is differentially high and low, respectively." (PMID 41348261, 2025).
vibratory urticaria (3 papers, 2017 to 2019). This very rare form of angioedema develops in reply to contact with vibration. "Intriguingly, a point mutation in the GAIN domain of ADGRE2 sensitizes the receptor to mechanical stimuli in kindreds of patients suffering from vibratory urticaria." (PMID 28784204, 2017).
polymicrogyria (2 papers, 2011 to 2017). A developmental brain abnormality characterized by an excessive amount of small convolutions on the surface of the brain and cognitive dysfunction. "For example, dysfunction of ADGRG1/GPR56 causes polymicrogyria, ADGRF5/GPR116 controls pulmonary surfactant production, genetic lesions in many aGPCR loci are associated with a roster of cancer types and ADGRE2/EMR2 regulates mast cell degranulation." (PMID 28784204, 2017).
alcohol (1 paper, 2023). "We observe positive colocalization [posterior probability (PP) > 80%] for 5 of 18 proteins with the same traits (ADGRE2 and total cholesterol [TC]; ANGPTL7 and BMI, waist-hip ratio; ITGB7 and TC; NOMO1 and LDL, TC; SEMA3F and BMI, alcohol use), supporting the two-sample MR results." (PMID 37550624, 2023).
IgA nephropathy (1 paper, 2018). "A role of these genes in vascular and/or inflammation-mediated kidney diseases is further substantiated by the associations with diabetes nephritis (ADGRE1, ADGRE5), lupus nephritis (ADGRE1, ADGRE2, ADGRE5), renal vasculitis (ADGRE2, ADGRE5), IgA nephropathy (ADGRE5) and renal hypertension (ADGRE5)." (PMID 29468160, 2018).
liver cancer (1 paper, 2022). An epithelial or non-epithelial malignant neoplasm that arises from the liver. "Moreover, nine activated memory CD4 T cell-related genes were associated with liver cancer prognosis [e.g., eomesodermin (EOMES), glutathione S-transferase (CST7), and adhesion G protein-coupled receptor E2 (EMR2)]." (PMID 34980144, 2022).
ADGRE2 also shares sentences with these, for which no sentence is quoted: systemic inflammatory response syndrome (6 papers); tumor (6); cancer (4); lung carcinoma (4); rheumatoid arthritis (4); Sepsis (3); glioma (2); multiple sclerosis (2); Acute Lymphoblastic Leukaemia (1); adenocarcinoma (1); airway hyperresponsiveness (1); Allergy (1); asthma (1); bladder cancer (1); breast carcinoma (1); colorectal carcinoma (1); congenital heart defects (1); endometriosis (1); endotoxemia (1); familial cold autoinflammatory syndrome (1); glioblastoma (1); hereditary angioedema (1); immune dysfunction (1); invasive carcinoma (1); kidney diseases (1); leukaemia (1); liver cirrhosis (1); lupus nephritis (1); metabolic syndrome (1); neurodevelopmental disorder (1).
A further 5 diseases each share a sentence with ADGRE2 in 1 paper.